SIRT7 (sirtuin 7)
Diseases named in the same sentence as SIRT7 in open-access papers (continued):
Sharing a sentence is not in itself a finding about the gene and the disease.
cancer (continued). "It interferes with SIRT7 activity by competing for the NAD+ binding site, which ultimately impairs DNA damage repair processes and reduces the survival of cancer cells." (PMID 41304967, 2025). "In addition to these mechanisms, SIRT7 may act as a key regulator of anti-cancer immune responses by controlling lipid metabolism, whose dysregulation in cancer cells leads to fatty acid accumulation within the TME, thereby profoundly influencing immune activity." (PMID 41471367, 2025). "Overall, these findings suggest that while SIRT7 supports anti-tumor immunity—partly by regulating metabolic programs in T cells—it may also reshape the tumor microenvironment through distinct metabolic networks operating in cancer cells, especially when its expression is deregulated." (PMID 41471367, 2025). "Moreover, by controlling molecular pathways such as metabolism, genomic stability, and inflammatory responses—both within cancer cells and across other components of the tumor microenvironment—SIRT7 may more broadly influence the immune landscape, orchestrating immune evasion or recognition." (PMID 41471367, 2025). "The NAD+-dependent deacetylase SIRT7 is a pivotal regulator of DNA damage response (DDR) and a promising drug target for developing cancer therapeutics." (PMID 38947512, 2024). "This axis is turned in favor of cancer cells by ribosomal L1 domain containing 1 (RSL1D1), which competitively binds to SIRT7 and inhibits RAN deacetylation." (PMID 37676263, 2024). "Recently, we discovered that SIRT7 destabilizes the cyclin dependent kinase inhibitor 2A (CDKN2A, known as ARF) within the nucleolus, aiding cancer progression." (PMID 39036727, 2024). "We propose that disruption of SIRT7–ARF signaling stabilizes ARF and thus attenuates cancer cell proliferation, offering a strategy to mitigate NSCLC progression." (PMID 38870055, 2024). "SIRT7 is an NAD+-dependent deacetylase that targets H3K18Ac, stabilizing the transformed state of cancer cells." (PMID 38894712, 2024). "SIRT1 helps cancer cells survive chemotherapy, SIRT2 inhibits cell growth, and SIRT3 controls mitochondrial health, while SIRT4, SIRT5, SIRT6, and SIRT7 each influence metabolism, angiogenesis, and metastasis." (PMID 39682281, 2024). "SIRT7 (sirtuin 7) is a member of the NAD+-dependent deacetylases and its role in cancer is controversial." (PMID 35317831, 2022). "In contrast to SIRT7, the ectopic expression of nuclear HDAC6 in NSCLC cells inhibits cancer invasiveness by the deacetylation of p65, which, in turn, decreases its binding to the matrix metalloproteinase-2 (MMP2) promoter and reduces MMP2 expression." (PMID 34769241, 2021). "We found that SIRT7 compromises SKP2-mediated AKT activation in the cytoplasm, thus inhibiting malignant tumor progression." (PMID 34433808, 2021). "Thus, SIRT7 might have opposing effects on cancer initiation and progression." (PMID 34129782, 2021). "In this study, we performed a comprehensive pan-cancer analysis on four well-known succinylation regulators (CPT1A, KAT2A, SIRT5, and SIRT7)." (PMID 33681201, 2021). "Findings from several studies have indicated that SIRT7 combines with chromatin and catalyzes the selective deacetylation of H3K18, an epigenetic biomarker of malignant tumors and an indicator of poor prognosis in patients." (PMID 33274232, 2020). "SIRT7 was initially identified as a histone deacetylase capable of removing acetyl groups from acetylated H3K18 and H3K36 in cancer cells and more recently reported as a histone desuccinylase for H3K122 residues across commonly used cell lines." (PMID 32504224, 2020). "The expression of SIRT4 and SIRT5 were down-regulated in cancer tissues, while SIRT6 and SIRT7 were up-regulated." (PMID 32158696, 2020).
cancer (continued). "Here, we used LNCaP and 22Rv1 cancer cells expressing endogenous AR and PSA to examine the relationship between AR and SIRT7 and the effects of the latter on AR signaling-mediated cancer proliferation and aggressiveness." (PMID 32019578, 2020). "In 72 paired KIRC tissues and corresponding adjacent normal tissues, expressions of SIRT4 and SIRT5 were down-regulated in cancer tissues than in normal tissues, while expressions of SIRT6 and SIRT7 were up-regulated in cancer tissues." (PMID 32158696, 2020). "Our findings thus highlight the importance of the SIRT7 in HCC carcinogenesis and identify SIRT7 as a potentially useful target for the development of mechanism-based cancer therapeutic strategies." (PMID 31196136, 2019). "Thus, SIRT7 may be of vital importance for cancer-cell metastasis." (PMID 30510540, 2018). "Among the known substrates of SIRT7 are PAF53, NPM1, GABP-β1, but more importantly, SIRT7 catalyzes the deacetylation of lysine 18 on histone H3 (H3K18), a marker of cancer aggressiveness and poor prognosis." (PMID 29100388, 2017). "Our study, taken together with these evidences, proposes that SIRT7 overexpression in cancer including HCC has important clinico-pathological implications, including value of SIRT7 as a prognostic and therapeutic candidate." (PMID 26442981, 2015). "Although its role in B cell-mediated tumor immunity remains insufficiently defined, the SIRT7–Pax5 axis may represent a possible mechanism of B cell regulation within the TME, with important implications for anti-cancer immunity." (PMID 41471367, 2025). "Given SIRT7’s central role in activating DNA repair mechanisms and maintaining genome integrity, it is not surprising that its upregulation enhances cancer cell survival following treatment with DNA-damaging agents." (PMID 41471367, 2025). "Such dualism suggests that SIRT7 is oncogenic in cancer but protective in non-malignant tissue conditions, particularly under conditions of chemotherapeutic stress." (PMID 41425553, 2025). "Research has also shown that SIRT7 depletion reduces PC3 cell migration without affecting cancer cell proliferation." (PMID 40165597, 2025). "Although this evidence suggests a potential tumor-suppressive role for SIRT7 in these cancers, rigorous experimental validation is still lacking, and the mechanisms underlying these putative effects remain to be addressed." (PMID 41471367, 2025). "Sirtuin 7 (SIRT7), a member of the mammalian family of NAD+-dependent histone/protein deacetylases, collectively known as sirtuins, regulates various biological functions and has recently been recognized as a critical factor in controlling cancer progression." (PMID 39036727, 2024). "Given that the polyubiquitination of AKT facilitates its localization to the cell membrane to trigger its activation, through this mechanism SIRT7 effectively curtails the AKT signaling cascade, which, in turn, plays a pivotal role in fueling cancer cell survival, driving the progression of cancer." (PMID 38383727, 2024). "This conserved regulatory mechanism indicates that the regulation of UPR by SIRT7 via SMAD4 might also be similar in other types of cells and cancers." (PMID 36918544, 2023). "Elevated SIRT7 deacetylated the lysine 18 of histone H3 (H3K18), promoted the enrichment of SIRT7 at the promoters, and inhibited the expression of tumor suppressors to fuel cancer progression." (PMID 36291918, 2022). "Consistent with the cooperative action between SIRT1 and SIRT6, independent studies have revealed an interaction between SIRT1 and SIRT7, showing that SIRT1 recruits SIRT7 to promote cancer cell metastasis, and that SIRT1 and SIRT7 antagonistically regulate adipogenesis." (PMID 32538779, 2020).
cancer (continued). "At chromatin, SIRT7 catalyzes selectivedeacetylation of lysine 18 on histone H3 (H3K18), an emerging epigenetic biomarker ofaggressive tumors and poor clinical outcome in cancer patients." (PMID 25923013, 2015). "Although no specific SIRT7 activators have been identified, most current efforts focus on developing selective SIRT7 inhibitors, reflecting its predominantly pro-tumorigenic activity in many cancers." (PMID 41471367, 2025). "Overexpression of ELK4 can increase SIRT7 levels at specific TSG loci, maintaining low acetylation levels of H3K18 at multiple TSG promoters, thus contributing to tumorigenesis and maintaining the malignant phenotype of cancer cells, correlating with poor patient prognosis." (PMID 40165597, 2025). "Furthermore, the deacetylation of SMAD4 through SIRT7 has the potential to function as a blocker for TGF-β, which may be of relevance when targeted therapy is needed for appropriate individuals with cancer." (PMID 38316768, 2024). "Consequently, SIRT7 propels the activation of SIRT1, initiating SIRT1-mediated deacetylation and activation of the AKT/p70S6K1 signaling cascade that in turn stimulates the growth and survival of cancer cells." (PMID 38383727, 2024). "Therefore, SIRT7 and SIRT1/SIRT6 play opposite roles in the metabolism, inflammation, and cancer." (PMID 36012298, 2022). "An important cellular function of SIRT7 is regulation of the chromatin remodelling: it catalyses the selective deacetylation of lysine 18 on histone H3 (H3K18), an emerging histone biomarker of aggressive tumours and poor clinical outcome in patients with cancer." (PMID 35422493, 2022). "Beside the role of SIRT7-mediated H3K18 deacetylation in maintaining a malignant phenotype, Pandey & Kumar provided evidence that HBx-dependent accumulation of SIRT7 favours H3K18 deacetylation and downregulation of RPS7, which is involved in the DDR and cancer cell transformation." (PMID 34129782, 2021). "The lysine acetylation regulators with CNV amplification showed significantly higher expression in cancer cells when compared to normal cells (e.g. KAT2A and ATAT1), while the regulators with CNV deletion showed significantly lower expression (e.g. SIRT6 and SIRT7)." (PMID 34136387, 2021). "However, no study has reported the effect of SIRT7 on OSCC, so the underlying mechanism of this cancer remains elusive." (PMID 30001742, 2018). "However, it must be noted that SIRT7 is required only to sustain cancer phenotype and does not promote oncogenic transformation of normal cells." (PMID 28258519, 2017). "On the whole, it would not be inappropriate to speculate potential roles of SIRT7 in maintaining metabolic homeostasis, cancer metabolism, and thus anti-aging process." (PMID 25907989, 2015). "Importantly, we use a system in which the role of SIRT7 in regulating themetastatic potential of cancer cells in vivo can be examined without potentialconfounding effects of SIRT7 on intrinsic primary tumor growth." (PMID 25923013, 2015). "Knockdown of Sirt7 expression in human breast MCF-7 cell line by siRNA induced premature senescence-like phenotype and multi-drug resistance, suggesting that this gene may play an active role in regulating cancer cell response to stress." (PMID 24885964, 2014). "Thus, it is not suitable to use PC3 or DU145 cells to study whether SIRT7 affects cancer cell proliferation and invasion by influencing the AR signaling pathway." (PMID 32019578, 2020). "However, on subdividing the cancer biopsies by nodal status, SIRT3 expression, like that of SIRT7, was greater in node-positive breast cancer compared to normal breast tissue." (PMID 17003781, 2006).
tumor (124 papers, 2006 to 2026). "This is reflected by a higher burden of cancerous lesions and greater tumor size in SIRT7-deficient mice compared with their wild-type littermates." (PMID 41471367, 2025). "While some studies report that SIRT7 depletion suppresses proliferation and migration through activation of the p38 MAPK pathway, others show that loss of SIRT7 accelerates tumor growth in mouse models, underscoring its context-dependent role." (PMID 41471349, 2025). "High levels of SIRT7 in these malignancies associate with a more aggressive phenotype and correlate with the stage of tumor progression." (PMID 38383727, 2024). "The regulatory influence of O-GlcNAcylation on SIRT7 underscores its significance in modulating the critical pathways associated with tumor aggressiveness, thereby revealing opportunities for targeted interventions." (PMID 39682281, 2024). "SIRT7, in particular, stands out for its association with aggressive tumor phenotypes, offering significant promise in predicting disease prognosis." (PMID 39796040, 2024). "SIRT7 expressions were positively associated with advanced N stages, clinical pathological stages and tumor grades." (PMID 37691108, 2023). "Aside from direct regulation of tumor cell behavior, the results from xenograft tumor in immune-competent mice showed increased CD8+T cells infiltration in TME in the tumor with SIRT7 deficiency." (PMID 36918544, 2023). "By reducing H3K18Ac, SIRT7 O-GlcNAcylation has been associated with repressing tumor suppressor genes to promoting tumor progression in nude mice." (PMID 38093337, 2023). "As a result, in response to systemic HA15 administration, the deficiency of tumorous SIRT7 prominently delayed the growth of implanted B16F10 tumor." (PMID 36918544, 2023). "For instance, high expression of SIRT1 and SIRT7 is highly associated with poor survival, whereas low tumor levels of SIRT4 predicts a decreased survival time in HCC patients." (PMID 36581622, 2022). "A previous study identifies that low levels of nuclear SIRT7 expression are associated with an aggressive tumour phenotype and poorer outcome." (PMID 35422493, 2022). "As radiation resistance is associated with tumor aggressiveness, we explored the role of SIRT7 in the radiation sensitivity of PCa cells." (PMID 32019578, 2020). "SIRT7 levels have been found to be elevated in tumors and positively associated with the tumor grade." (PMID 31121824, 2019). "SIRT7 expression is also upregulated in a large cohort of HCC patents and SIRT7 expression is associated with increased tumor grade." (PMID 31196136, 2019). "As a tumor suppressor, low levels of SIRT7 are associated with aggressive tumor phenotypes and poor patient outcomes." (PMID 30510540, 2018). "There are also studies that indicate that Sirt7 can be phosphorylated and that it is associated with many signaling pathways in certain tumor cell models." (PMID 28582407, 2017). "An association was found between SIRT7 expression and tumor grade with a higher mean Allred Score in the Gleason Score 7 tumors (p = 0.035) and Gleason Score ≥ 8 (p = 0.015) compared with Gleason Score 6 tumors." (PMID 29100388, 2017). "Initially identified as an activator of RNA polymerase I, SIRT7 is now also linked to tumor transformation by controlling cellular proliferation and survival." (PMID 26798421, 2016). "Low levels of nuclear SIRT7 expression were also associated with an aggressive tumour phenotype and poorer outcome, as measured by disease-free and disease-specific survival time, 12 months post-diagnosis." (PMID 26121130, 2015). "Low levels of both cytoplasmic and nuclear SIRT7 were linked with tumours that had R1 resections (<1mm) (p = 0.039 & p = 0.017 respectively)." (PMID 26121130, 2015).
tumor (continued). "That suggests that higher SIRT7 levels may be associated with more aggressive tumor characteristics and poorer patient survival outcomes." (PMID 40710366, 2025). "Because T cells rely on tightly controlled levels of these metabolites to support activation and proliferation, loss of SIRT7 results in metabolic dysregulation, impaired expansion and activation, and the promotion of an exhausted phenotype that compromises anti-tumor immunity." (PMID 41471367, 2025). "The SIRT7 inhibitor 97,491 exerts its inhibitory effect on SIRT7 in vivo by upregulating caspase‐associated protein, thereby promoting apoptosis and inhibiting tumor growth." (PMID 40165597, 2025). "Likewise, SIRT6 and SIRT7 have been shown to promote tumor progression, with elevated expression linked to aggressive disease and poor survival, solidifying their potential as reliable biomarkers." (PMID 39796040, 2024). "We cannot discern whether these results indicated SIRT7 haploinsufficiency or loss of heterozygosity in Sirt7+/− tumor cells due to the heterogenicity of the samples." (PMID 38234684, 2023). "Our previous reports and current results indicate that SIRT7 knockout mice have a reduced life span compared to control mice, although the underlying cause of death, and whether it involves tumor formation, is uncertain." (PMID 38234684, 2023). "Moreover, overexpression of SIRT6 and SIRT7 was associated with tumor stage II and a better outcome." (PMID 31572453, 2019). "Additionally, low levels of cytoplasmic SIRT7 were associated with high grade tumours (p = 0.032)." (PMID 26121130, 2015). "The association of elevated SIRT7 expression in node-positive tumours, which have a greater recurrence and poorer survival, suggests that this gene may prove to be a good marker of disease progression and tumour behaviour." (PMID 17003781, 2006). "This apparent contradiction reveals a striking duality: while SIRT7 protects against tumor initiation, it can also promote tumor growth and progression once malignancy is established." (PMID 41471367, 2025). "Altogether, these findings underscore the dual role of SIRT7 in tumor biology, particularly through its control of DNA repair and genomic stability." (PMID 41471367, 2025). "Collectively, these observations underscore the tumor-specific nature of SIRT7-mediated immune regulation, particularly in modulating immune checkpoint pathways, which likely operate through distinct molecular programs." (PMID 41471367, 2025). "SIRT6 can regulate gene expression of DNA stability and immunity, while SIRT7 promotes tumor metastasis through upregulation of E-cadherin expression." (PMID 41011152, 2025). "Key findings include the superior efficacy of SOR and SIRT7 inhibitor-loaded NPs, achieving an eightfold tumor volume reduction compared to free drugs." (PMID 40278256, 2025). "Taken together, a potential tumour-suppressive role of SIRT7 in haematologic malignancies can be proposed." (PMID 40941028, 2025). "SIRT1, SIRT2, and SIRT7 have been implicated in the development and metastasis of EC, while SIRT6 has been shown to exhibit anti-tumor properties in this context." (PMID 41471349, 2025). "This duality reflects the context-dependent nature of SIRT7 signaling, which is likely influenced by the tumor lineage and interactions with co-regulatory proteins." (PMID 41425553, 2025).